YTHDC1 (YTH N6-methyladenosine RNA binding protein C1)
Diseases named in the same sentence as YTHDC1 in open-access papers (continued):
Sharing a sentence is not in itself a finding about the gene and the disease.
bladder cancer (continued). "Since GLUT3 is the downstream gene of YTHDC1 in bladder cancer cells, we next determined whether GLUT3 is one of the key mediators of YTHDC1-induced suppression of bladder cancer." (PMID 37258572, 2023). "Downregulation of YTHDC1 is negatively correlated with the outcome of patients with bladder cancer." (PMID 37258572, 2023). "Notably, silencing YTHDC1 in bladder cancer cells decreased the expression of PTEN and activated the PI3K/AKT pathway." (PMID 37915034, 2023). "As suggested, lower YTHDC1 expression in bladder cancer indicated worse overall survival." (PMID 37070134, 2023). "We found that YTHDC1 overexpression inhibited the proliferation of bladder cancer cells." (PMID 37258572, 2023). "Then, we studied how YTHDC1 regulates the expression of GLUT3 in bladder cancer cells." (PMID 37258572, 2023). "Besides, in bladder cancer cells, silencing YTHDC1 obviously reduced PTEN expression at both mRNA and protein levels." (PMID 37070134, 2023). "Low YTHDC1 expression indicated poor cisplatin sensitivity in bladder cancer patients." (PMID 37070134, 2023). "Treating patients with lower YTHDC1 expression levels with cisplatin combined with MK2206 could be a novel strategy to mitigate cisplatin resistance in bladder cancer." (PMID 37070134, 2023). "Notably, TCGA dataset analysis indicated that the hazard ratio of the expression of YTHDC1 was less than 1.00 in bladder cancer (P = 0.0132)." (PMID 37258572, 2023). "We provide novel evidence that PTEN/PI3K/AKT signalling pathway could be regulated by YTHDC1 in an m6A‐dependent manner and highlight a critical role of YTHDC1 in cisplatin resistance of bladder cancer." (PMID 37070134, 2023). "Moreover, rescuing the expression of YTHDC1 attenuated the proliferation-, migration-, and invasion-promoting effects induced by knockdown of YTHDC1 in bladder cancer cells." (PMID 37258572, 2023). "In addition, analysis with the ENCORI web tool indicated that the mRNA level of YTHDC1 was negatively correlated with that of GLUT3 in bladder carcinoma, testicular germ cell tumor, sarcoma, and lung squamous cell carcinoma." (PMID 37258572, 2023). "FTO, IGF2BP3, and YTHDC1 have a significant difference in bladder cancer and prognosis." (PMID 35251177, 2022). "In addition, our team found that YTHDC1 was downregulated in bladder cancer cell lines T24 and UM-UC3 and the overexpression of YTHDC1 significantly suppressed the proliferation and metastasis of bladder cancer (data not published)." (PMID 35501308, 2022). "Future research could explore YTHDC1 as a potential target for bladder cancer treatment." (PMID 39741187, 2025). "Hence, we next compared expression of YTHDC1 in a cohort of bladder cancer patients." (PMID 37070134, 2023). "Thus, we identified a novel YTHDC1/GLUT3/RNF183 feedback loop in bladder cancer cells." (PMID 37258572, 2023). "Thus, we hypothesized that RNF183 might be the bridge between GLUT3 and YTHDC1 degradation in bladder cancer cells." (PMID 37258572, 2023). "Thus, we hypothesized that GLUT3 might regulate the protein stability of YTHDC1 in bladder cancer cells." (PMID 37258572, 2023). "METTL14, YTHDC1, and WTAP may be protective factors for bladder cancer, the higher expressions were related to the longer overall survival of patients, while IGF2BP1-3, YTHDF1, LRPPRC, ALKBH5, and FTO were risk factors for bladder cancer." (PMID 37701836, 2023). "In bladder cancer, it was found that m6A RNA methylation regulators could participate in the malignant progression of bladder cancer, and a risk signature with three selected m6A RNA methylation regulators (FTO, YTHDC1, and WTAP) could serve as a promising prognostic biomarker." (PMID 33628782, 2021). "The findings of our present study suggest that XIAP and YTHDC1 interact to regulate the stability of MMP-2 mRNA and promote metastasis of bladder cancer." (PMID 40133252, 2025).
bladder cancer (continued). "Ectopic overexpression of XIAP promoted degradation of YTHDC1, and knockout of XIAP upregulated YTHDC1, which inhibited metastasis of bladder cancer." (PMID 40133252, 2025). "Meanwhile, in bladder cancer, AARS1-mediated lactylation promotes RNF183-mediated ubiquitination and the degradation of YTHDC1." (PMID 41008630, 2025). "Overall, this study provides new insights into the mechanism via which XIAP regulates metastasis of bladder cancer, demonstrating in particular that XIAP acts as a novel E3 ligase for YTHDC1." (PMID 40133252, 2025). "Transwell assays confirmed that knockdown of YTHDC1 in UMUC3 (KO-XIAP), T24T (KO-XIAP) and wild-type cells markedly reversed invasion of bladder cancer cells in comparison with control cells in vitro." (PMID 40133252, 2025). "Collectively, these findings demonstrate that XIAP is a critical regulator of YTHDC1 and pinpoint the XIAP/YTHDC1/MMP-2 axis as a promising target for the treatment of bladder cancer." (PMID 40133252, 2025). "These experiments revealed that XIAP promotes ubiquitination of YTHDC1, positively regulating expression of the MMP-2 and promoting metastasis of bladder cancer." (PMID 40133252, 2025). "They identified a novel epitranscriptomic mechanism where YTHDC1 regulates the PTEN/PI3K/AKT signalling pathway in an m6A‐dependent manner, affecting chemotherapeutic outcomes in bladder cancer." (PMID 39135292, 2024). "YTHDC1 regulates the positive expression of the PTEN/PI3K/AKT signaling pathway and enhances chemoresistance in bladder cancer." (PMID 39006762, 2024). "In contrast, overexpression of YTHDC1 inhibited the glycolytic process and decreased the ECAR but increased the OCR in bladder cancer cells." (PMID 37258572, 2023). "In bladder cancer, it has demonstrated that ALKBH5, IGFBP2-3, RBM15, RBMX, YTHDC1, and YTHDF had prognostic value." (PMID 37701836, 2023). "In summary, we identified a novel YTHDC1/GLUT3/RNF183 feedback loop that regulates disease progression and glucose metabolism in bladder cancer." (PMID 37258572, 2023). "Taken together, these results suggest that silencing YTHDC1 suppresses autophagy to promote cisplatin resistance and DNA repair via destabilizing SQSTM1 in bladder cancer." (PMID 37070134, 2023). "Taken together, these results demonstrate that YTHDC1 regulates glucose metabolism and suppresses the expression of GLUT3 in bladder cancer cells." (PMID 37258572, 2023). "For the limitation of sample size, stageI was excluded for analysis of YTHDC1, FTO and WTAP mRNA expression between bladder cancer and the normal controls." (PMID 34521394, 2021). "We analyzed the RNA-Seq data for YTHDC1, FTO and WTAP in different stages (TNM) of bladder cancer samples from TCGA (412 bladder cancer and 19 normal samples)." (PMID 34521394, 2021). "Furthermore, the ectopic overexpression of X-linked inhibitor of apoptosis protein (XIAP) promotes the degradation of YTHDC1, whereas genetic ablation of XIAP elevates YTHDC1 expression, thereby suppressing metastatic progression in bladder cancer." (PMID 40986143, 2025). "We then investigated data for 19 pairs of patients with bladder cancer in The Cancer Genome Atlas database (TCGA) and found that expression levels of YTHDC1 and AKAP11 in bladder cancer tissue were downregulated in comparison with those in adjacent normal tissues." (PMID 40133252, 2025). "In HT1376 and RT112 cells (human bladder cancer cells), the inhibition of AARS1 suppressed the lactylation of YTH N6-methyladenosine RNA-binding protein C1 (YTHDC1) and promoted the protein levels of YTHDC1." (PMID 41008630, 2025). "In bladder cancer (BLCA), NSUN2, IGF2BP2, YTHDC1, ALKBH5, TRDMT1, and ZC3H13 were identified, with NSUN2—a 5-methylcytosine (m5C) writer—previously shown to promote tumorigenesis and cancer stemness by stabilizing CCND1 mRNA and driving epithelial–mesenchymal transition." (PMID 40565233, 2025).
bladder cancer (continued). "Then, we showed that YTHDC1 participates in regulating glucose metabolism and that this effect might be mediated by GLUT3 downregulation in bladder cancer cells." (PMID 37258572, 2023). "Therefore, we identified a novel YTHDC1/GLUT3/RNF183 feedback loop that regulates disease progression and glucose metabolism in bladder cancer." (PMID 37258572, 2023). "In contrast, overexpression of GLUT3 reduced the protein level but not the mRNA level of YTHDC1 in bladder cancer cells." (PMID 37258572, 2023). "Then, we found that YTHDC1 was significantly downregulated in bladder cancer tissues compared with nontumor tissues in the TCGA dataset, in specimens from our hospital and in a bladder cancer tissue microarray obtained from Bioaitech (#U100Bl01)." (PMID 37258572, 2023). "We also used the immunohistochemical results of Human Protein Atlas database to explore the expression of independent prognostic factor in bladder cancer and found that YTHDC1 and FTO levels in normal bladder tissues were significantly higher than in bladder cancer tissues." (PMID 34521394, 2021).
acute myeloid leukemia (20 papers, 2021 to 2025). Acute myeloid leukemia (AML) is a group of neoplasms arising from precursor cells committed to the myeloid cell-line differentiation. "YTHDC1-IN-1 functions as a specific inhibitor of YTHDC1 and has antiproliferative effects on acute myeloid leukemia cells." (PMID 40986143, 2025). "For example, YTHDC1 undergoes LLPS requiring m6A, and the nuclear YTHDC1–m6A condensates maintain cell survival and the undifferentiated state of acute myeloid leukemia cells." (PMID 39006762, 2024). "RNA-binding protein YTH N6-methyladenosine RNA binding protein C1 (YTHDC1) is highly expressed in many cases of acute myeloid leukemia and is a new potential target for treating this disease." (PMID 38481812, 2024). "We alsoreport a direct connection between YTHDC1 inhibition and antiproliferativeactivity on acute myeloid leukemia cell lines (THP-1, MOLM-13, NOMO-1)." (PMID 38787793, 2024). "This interaction results in the formation of nuclear YTHDC1-m6A condensates (nYACs), which are significantly enhanced in acute myeloid leukemia (AML) cells." (PMID 38110976, 2023). "Compared to normal blood cells, YTHDC1 condensates are more abundant in acute myeloid leukemia (AML) cells to maintain cell survival and an undifferentiated myeloid state." (PMID 36117111, 2022). "The reader YTHDC1 was reported as a suppressor gene in pancreatic cancer but an oncogene in acute myelocytic leukemia." (PMID 34631793, 2021). "Additionally, YTHDC1 is overexpressed and exhibits oncogenic functions in acute myeloid leukemia (AML)." (PMID 40271153, 2025). "YTHDC1 has been shown to promote endometrial cancer, glioblastoma, and acute myeloid leukemia (AML) progression 27-31; however, its role in breast cancer remains unknown." (PMID 35966596, 2022). "YTHDC1 also serves a role in differentiation as Ythdc1 expression was increased in M0 undifferentiated acute myeloblastic leukemia cells, suggesting that YTHDC1 may be required to maintain an undifferentiated state." (PMID 35350378, 2022). "Additionally, YTHDC1 expression is robustly induced in leukemic stem cells, which may be correlated with adverse clinical outcomes in acute myeloid leukemia patient." (PMID 40986143, 2025). "Recently, YTHDC1 was found to be elevated in acute myeloid leukemia (AML) and to be essential for the survival and development of AML cells." (PMID 37258572, 2023). "In liquid-liquid phase separation (LLPS), YTHDC1-m6A forms condensates in acute myeloid leukemia (AML) cell lines, and YTHDC1 m6A-binding mutants display puncta formation and cell proliferation defects." (PMID 40242544, 2025). "The m6A is required for YTHDC1 to undergo LLPS and form nuclear aggregates, where the number of nuclear YTHDC1-m6A aggregates is higher in acute myeloid leukemia than in normal hematopoietic stem cells." (PMID 35875144, 2022). "YTHDC1 realized oncogenic RNA splicing of tumor suppressor RBM4 during progression of cancer and was found to control the DNA replication regulator MCM4, which promotes proliferation and survival of acute myeloid leukemia cells." (PMID 40133252, 2025). "Furthermore, in acute myeloid leukemia (AML) cells, YTHDC1 binds to m6A RNAs and forms liquid-like condensates in the nucleus, and the condensates protect a set of PAXT target RNAs from degradation." (PMID 34948199, 2021). "Conversely, we also observed that YTHDC1 modulates the expression of MCM2, MCM4, and MCM5 in acute myeloid leukemia (AML) cells by controlling their mRNA stability." (PMID 39414764, 2024).
glioma (17 papers, 2020 to 2024). A benign or malignant brain and spinal cord tumor that arises from glial cells (astrocytes, oligodendrocytes, ependymal cells). "We also found that YTHDC1 rs2293595 was associated with a significant inverse association with risk of glioma." (PMID 34897032, 2021). "For instance, YTHDC1 interacts with the circRNAs from the EPHB4 gene, which is implicated in glioma." (PMID 38474421, 2024). "Zhu el al reported YTHDC1-mediated VPS25 regulated the cell cycle by activating the JAK-STAT signaling pathway in human glioma cells." (PMID 38978074, 2024). "On the other hand, YTHDC1 was reported to impede the proliferation of glioma by downregulating the expression of VPS2530." (PMID 37258572, 2023). "In glioma, studies found the m6A-SNPs, rs7766006 (WTAP), rs3738067 (YTHDF2), and rs9939609 (FTO), to increase cancer risk, whereas rs2293595 (YTHDC1), rs3813832 (YTHDC1), and rs8047395 (FTO) reduced the risk." (PMID 34151731, 2021). "We also demonstrated that YTHDC1 affects the proliferation of glioma cells by regulating VPS25 expression." (PMID 34863175, 2021). "We decreased VPS25 expression in METTL3, METTL14, and YTHDC1 KD glioma cells, and a series of restoration assays were performed." (PMID 34863175, 2021). "In the intricate network of glioma pathogenesis, the YTHDF family, consisting of YTHDF1, YTHDF2, and YTHDF3, and YTHDC1 and YTHDC2, as members of the YTH domain-containing family, play significant roles in the prognosis and molecular mechanisms underlying glioma." (PMID 38474421, 2024). "YTHDC1 affects glioma cell proliferation, cell cycle and apoptosis via the JAK-STAT pathway." (PMID 38171932, 2023). "Meanwhile, the expression level of YTHDC1 was dramatically decreased in high-grade gliomas." (PMID 34631793, 2021). "We then speculated that METTL3, METTL14, and YTHDC1 might affect the proliferation of glioma cells through VPS25." (PMID 34863175, 2021). "Together, these results indicate that YTHDC1 may inhibit glioma proliferation by reducing VPS25 expression." (PMID 34863175, 2021). "Meanwhile, YTHDC1 was a potential protective factor in glioma." (PMID 34631793, 2021). "However, YTHDC1 was reported to suppress the progression of glioma by inhibiting VPS25." (PMID 35974388, 2022). "Finally, YTHDC1 inhibited glioma proliferation by reducing the expression of VPS25." (PMID 34863175, 2021). "YTHDC1 and YTHDC2 are integral components in the molecular landscape of glioma, influencing various aspects of tumor biology." (PMID 38474421, 2024). "YTHDC1 reduces the expression of VPS25 and inhibits glioma proliferation through the JAK-STAT signaling pathway." (PMID 37964279, 2023). "Subsequently, the differential analysis showed that, between glioma and normal brain tissue, a variety of m6A-related genes were differentially expressed, including METTL14, METTL16, ZC3H13, YTHDC1, YTHDC2, YTHDF2 etc." (PMID 35559019, 2022). "Additionally, YTHDC1 influences glioma cell proliferation through its impact on VPS25, a protein upregulated in gliomas." (PMID 38474421, 2024). "The YTHDC1/circPOLR2B/POLR2B/PBX1 axis plays a regulatory role in the biological behavior of GSCs, offering potential targets and novel strategies for the treatment of glioma." (PMID 39090090, 2024). "The m6A quantitative analysis showed that the METTL3 and METTL14 KD decreased the total m6A modification level in glioma cells, whereas the YTHDC1 KD did not." (PMID 34863175, 2021). "Furthermore, METTL3, FTO, and YTHDC1 were higher in IDH-mutant LGG and GBM than in wild-type gliomas; however, this did not mean that the RNA was more or less methylated (more than m6A/m5C) in IDHm gliomas." (PMID 37964279, 2023). "The mRNA level of VPS25 was upregulated in glioma cells with KD of METTL3 or METTL14, but it was not affected in the YTHDC1 KD cells." (PMID 34863175, 2021). "However, the protein level of VPS25 was not affected in glioma cells with KD of METTL3 or METTL14, but it was upregulated in the YTHDC1 KD cells." (PMID 34863175, 2021).